AHR (aryl hydrocarbon receptor)
Diseases named in the same sentence as AHR in open-access papers (continued):
Sharing a sentence is not in itself a finding about the gene and the disease.
liver fibrosis (continued). "IL-22RA1 knockout mice or mice with blockade of IL-22/IL-17 production by RAR-related orphan receptor gamma-t (RORγt) or aryl hydrocarbon receptor (AhR) antagonists exhibit reduced liver fibrosis." (PMID 34944732, 2021). "Increasing evidence supports a role for endogenous AhR signaling in regulating collagen deposition, including the discovery that AhR knockout mice develop liver fibrosis and have elevated TGF-β1 and collagen expression." (PMID 27672655, 2016). "Most current research on AhR in hepatic fibrosis focuses on preventing fibrosis progression." (PMID 41585883, 2025). "Furthermore, this study elucidated the molecular mechanism by which AHR alleviates liver fibrosis and provides a potential target for the treatment of liver fibrosis." (PMID 39654034, 2024). "Spontaneous liver fibrosis can be observed in AHR‐knockout mice." (PMID 39654034, 2024). "In conclusion, we demonstrated that AHR is an important transcription factor in liver fibrosis." (PMID 39654034, 2024). "In a chronic liver fibrosis model, AHR alleviated liver fibrosis by facilitating ferroptosis in mHSCs without causing hepatocyte ferroptosis." (PMID 39654034, 2024). "Our findings suggest that AHR may represent a promising target for the prevention and treatment of liver fibrosis." (PMID 39654034, 2024). "In a chronic liver fibrosis model, YH439 activated AHR to promote mHSC ferroptosis without causing hepatocyte ferroptosis, thereby alleviating liver fibrosis." (PMID 39654034, 2024). "Conversely, the activation of AHR by TCDD can induce liver fibrosis in mice." (PMID 39654034, 2024). "Conclusively, this study shows that AHR alleviates liver fibrosis in mice by selectively inducing mHSC ferroptosis without causing hepatocyte ferroptosis and suggests that AHR is a potential target for the treatment of liver fibrosis." (PMID 39654034, 2024). "Moreover, TCDD treatment for 2 weeks elevated the hepatic expression of fibrotic markers and a 6-week TCDD regimen induced liver fibrosis in mice in an AhR-dependent manner." (PMID 37284280, 2023). "Therefore, a role of AhR signaling in hepatic fibrogenesis is critical but complex, and additional studies are required to completely uncover AhR function in liver fibrosis." (PMID 37284280, 2023). "Considering that there are multiple cell types in the liver, including hepatocytes, hepatic stellate cells and Kupffer cells, it is reasonable to postulate that AhR may have a cell type-specific role in hepatic fibrosis." (PMID 35656117, 2022). "Specifically, knockout of AhR in HSCs causes spontaneous liver fibrosis; in contrast, a non-toxic AhR agonist exhibited in vivo anti-fibrotic activity in mice." (PMID 34441435, 2021). "However, the role of AHR in liver fibrosis remains controversial." (PMID 39654034, 2024). "This may explain why AHR alleviates liver fibrosis in mice by promoting ferroptosis in mHSCs without causing hepatocyte ferroptosis." (PMID 39654034, 2024). "Developing nontoxic agonists of AHR and investigating their underlying mechanisms may have positive implications for the prevention or treatment of liver fibrosis." (PMID 39654034, 2024). "Moreover, in the CCl4 model, application of ITE could prevent fibrosis induction, suggesting AHR in HSCs as a potential target for the treatment of liver fibrosis." (PMID 34075438, 2021). "Moreover, given that AHR is widely expressed throughout the body and has pleiotropic functions, targeting strategies for specific delivery of AHR agonists or antagonists to the relevant target cells, such as HSCs in liver fibrosis or APCs in immune-mediated diseases, are highly desirable." (PMID 34075438, 2021). "However, in another study, an adverse effect of AHR in liver fibrosis has been observed." (PMID 34075438, 2021). "Conversely, the nontoxic endogenous ligand 2‐(1H‐indole‐3‐carbonyl)‐thiazole‐4‐carboxylic acid methyl ester (ITE) activates AHR, which inhibits HSC activation and inhibit liver fibrosis in mice." (PMID 39654034, 2024).
liver fibrosis (continued). "This study aimed at investigating the potential therapeutic roles of AHR and HSC ferroptosis in liver fibrosis." (PMID 39654034, 2024). "The snRNA-seq data used for this study 18 was obtained from mice chronically exposed to the AhR agonist ligand TCDD over a 4-wk period, which results in hepatic lipid accumulation and promotes progression to steatohepatitis with liver fibrosis." (PMID 36711947, 2023). "In human liver, the mRNA expression of AhR target genes CYP1A1 and CYP1A2 is decreased in patients with hepatic fibrosis." (PMID 37284280, 2023). "Although various AHR agonists, including TCDD, FICZ, and Bap, have demonstrated therapeutic potential in in vitro models, their use can lead to severe complications such as liver fibrosis, embryo mortality and carcinogenesis." (PMID 39125717, 2024). "This study revealed that YH439 specifically promotes ferroptosis in mHSCs by activating AHR without inducing ferroptosis of hepatocytes, thus alleviating liver fibrosis." (PMID 39654034, 2024). "Developing non-toxic AhR agonists or strategies to activate AhR signaling in HSCs could be used to prevent or treat liver fibrosis." (PMID 41019044, 2025). "The development of nontoxic AHR agonists and the investigation of their mechanisms of action may have positive implications for the prevention or treatment of liver fibrosis." (PMID 39654034, 2024). "On the one hand, AhR has a great influence on liver development, and mice lacking AhR showed spontaneous hepatic fibrosis with significant liver architecture alteration, suggesting that the basal AhR activity may suppress fibrotic phenotypes in vivo." (PMID 35656117, 2022). "Therefore, we conclude that reduced AhR signaling is at least partially responsible for the lack of immune signaling, and hence, accumulation of hepatic fibrosis in GNMT‐/‐ mice." (PMID 32951289, 2020). "Sustained exposure to TCDD results in hepatic fibrosis in mice, which is dependent on AHR and is therefore not observed in Ahr−/− mice." (PMID 34129049, 2021).
lung adenocarcinoma (29 papers, 2009 to 2025). A carcinoma that arises from the lung and is characterized by the presence of malignant glandular epithelial cells. "Low intratumoral AHR expression associates with inferior outcome of patients with resected lung adenocarcinomas." (PMID 33214553, 2020). "CYP1A1 expression has further been reported in 40 out of 107 human lung adenocarcinomas and 21 out of 57 mixed bronchioalveolar carcinomas by immunohistochemistry, whereas the expression of both AhR and CYP1A1 was associated with smoking in lung adenocarcinoma patients." (PMID 19531241, 2009). "Thymol and anti-PD-1 antibodies therapy suppresses IL4I1 and AhR signaling in lung adenocarcinoma models." (PMID 40559961, 2025). "AhR knockout has been also shown to increase inflammatory signaling in lung adenocarcinoma A549 cells." (PMID 37696458, 2023). "By an unbiased shRNA screen in H1975 human lung adenocarcinoma cells, AHR was uncovered as a major anti-metastatic factor through restraining the expression of TGFβ and some genes in EMT and invasion of the tumor cells." (PMID 37151890, 2023). "It has been reported that increased AHR protein levels inhibit ferroptosis in human lung adenocarcinoma PC-9 cells by increasing the expression of SLC7A1, a molecule that suppresses ferroptosis by reducing the reactive oxygen species content." (PMID 37894798, 2023). "Collectively, these findings indicate that suppression of AHR enhances the invasive capacity and adaptation to metabolic stress of lung adenocarcinoma cells." (PMID 33214553, 2020). "The current data indicated that elevated Notch1 induced higher IL-22 secretion by CD4+ T cells in lung adenocarcinoma patients, and Notch-AhR-IL-22 axis took part in the pathogenesis of lung adenocarcinoma." (PMID 30473538, 2018). "In conclusion, elevated Notch1 induced higher IL-22 secretion by CD4+ T cells in lung adenocarcinoma patients, and Notch-AhR-IL-22 axis took part in the pathogenesis of lung adenocarcinoma." (PMID 30473538, 2018). "The current data indicated the involvement of Notch-AhR-IL-22 axis in the pathogenesis of lung adenocarcinoma." (PMID 30473538, 2018). "However, the AHR positive rate is much lowered among the tissue samples of lung squamous cell carcinoma, lung adenocarcinoma and invasive lung cancer." (PMID 37151890, 2023). "Notably, AhR has been shown to play an active role in proliferation control in lung adenocarcinoma cells." (PMID 37696458, 2023). "For instance, BaP could activate and up-regulate the expression of aryl hydrocarbon receptor (AhR) in lung adenocarcinoma." (PMID 36771198, 2023). "Similarly, the RNA-Seq analysis of SARS-CoV-2-infected human lung adenocarcinoma Calu-3 cells detected the upregulation of AHR." (PMID 34446714, 2021). "The AhR overexpression upregulated the expression of CYP1B1 in the early stage of lung adenocarcinoma, which could increase intracellular oxidative stress and promote cell growth." (PMID 32626511, 2020). "Thus, the aim of current study was to investigate the involvement of Notch-AhR-IL-22 axis in the pathogenesis of lung adenocarcinoma." (PMID 30473538, 2018). "AhR expression is upregulated in lung adenocarcinoma, suggesting that AhR and its expression might play an important role in the development of lung adenocarcinoma." (PMID 27077888, 2016). "Interestingly, re-analyses of publicly available RNA expression data from patient cohorts with early-stage and locally advanced lung adenocarcinoma revealed that time-to-first-progression and overall survival were significantly reduced in patients with tumors exhibiting low AHR expression." (PMID 33214553, 2020). "which links AHR to IFN-γ-induced JAK/STAT pathway and immune checkpoint-mediated immunosuppression in lung adenocarcinoma." (PMID 41445756, 2025). "In lung adenocarcinoma, UCHL3 stabilizes the aryl hydrocarbon receptor (AhR), contributing to the acquisition of stemness features." (PMID 38965582, 2024).
lung adenocarcinoma (continued). "In this study, we also revealed down-regulation of IL-22 secretion and AhR mRNA expression, but comparable RORγt mRNA level, in lung-resident CD4+ T cells in response to Notch signaling inhibition in lung adenocarcinoma patients." (PMID 30473538, 2018). "Therefore, in the present study, we addressed the functional role of the AhR in control of inflammatory responses in a model of ATII-like cells, A549 lung adenocarcinoma cell line." (PMID 35203356, 2022). "In an elegant series of experiments Chen and colleagues showed that AhR could induce IL-6 expression and NF-κB activity in BEAS-2B cells and H1355 human lung adenocarcinoma cells." (PMID 25201625, 2014). "In the absence of exogenous ligands, AhR overexpression upregulated the expression of CYP1B1 in the early stage of lung adenocarcinoma." (PMID 25068070, 2013). "However, both RORγt and AhR was notably increased in BALF CD4+ T cells from tumor site in comparison with those from nontumor site in lung adenocarcinoma patients (P<0.0001)." (PMID 30473538, 2018). "Neither RORγt nor AhR mRNA showed remarkable changes in peripheral CD4+ T cells between NCs and lung adenocarcinoma patients (P=0.212 and 0.186, respectively)." (PMID 30473538, 2018).
skin cancer (28 papers, 2010 to 2025). "This UVB-induced AhR signaling activation and skin tumor formation was associated with the expression of cyclooxygenase-2 (COX-2) and the consequent DNA damage." (PMID 39211042, 2024). "This study demonstrated that environmental factors such as UV and/or PM activate various molecular targets including SFK and AhR and cause skin inflammation, photoaging, and skin cancer." (PMID 36983027, 2023). "Therefore, AhR activation by UVB-induced FICZ is believed to be the one important mechanism by which UVB causes skin cancer, by hampering DNA repair and apoptosis, and repressing the immune systems." (PMID 38518996, 2024). "In addition, it has been shown that AhR deficient mice are more protected against UV-induced skin cancer." (PMID 35458697, 2022). "This process induces aryl hydrocarbon receptors (AhR), leading to skin discomfort (e.g., tingling, itching, burning sensation, dryness, erythema, desquamation, papules, or scales), accelerated skin aging, disruption of the skin barrier function, and an increased risk of skin cancer." (PMID 40073012, 2025). "FICZ, derived from tryptophan metabolism after exposure to UV radiation of the sun, seems to be involved in skin cancer via the AhR activation." (PMID 35458697, 2022). "It is well established that skin cancer is the most common type of cancer in Caucasians, and AhR seems to play an important role in carcinogenesis as well as in the development of various types of skin cancer." (PMID 35458697, 2022). "Early studies pointed to a partial role of AhR in the pathogenesis of various skin diseases, including inflammatory diseases, skin pigmentation disorders, and skin cancer, as well as a dependence of the outcome of AhR activation on the cell type and ligand." (PMID 35743162, 2022). "It was suggested that the AhR signaling pathway is involved in the initiation of keratinocyte-derived skin cancers induced by UVB radiation." (PMID 33499346, 2021). "For example, some metabolites of tryptophan, an essential amino-acid that acts as the strongest natural near-UV-absorbing chromophore, represent a group of ligands for AhR involved in the induction and progression of skin cancer." (PMID 34944067, 2021). "In the following sections, we introduce the function of AHR in the context of carcinogenesis and maintenance of skin cancer and mainly focus on environmental carcinogens and molecular targeted therapy." (PMID 31552251, 2019). "Recent reports suggest that AHR plays an important role in carcinogenesis and maintenance of various types of skin cancers." (PMID 31552251, 2019). "The emergence of research investigating the effect of AHR antagonists for various skin cancers is promising and eagerly awaited." (PMID 31552251, 2019). "Recent findings show that AHR modulates anti-tumor immunity and proliferative signals in skin cancers." (PMID 31552251, 2019). "Development of therapeutic agents that modulate AHR activity is a promising strategy to advance chemoprevention and chemotherapy for skin cancers." (PMID 31552251, 2019). "This means that the AHR system is a putative target, particularly for chemoprevention and cancer chemotherapy of skin cancer." (PMID 31552251, 2019). "Regarding skin cancer, a genome-wide association study of cutaneous squamous cell carcinoma (SCC) also identified AHR as a novel susceptibility locus." (PMID 31552251, 2019). "Further studies are needed to investigate whether AhR is the target for carvedilol’s skin cancer preventive activity." (PMID 40270580, 2025). "Comprehensive reviews on AhR and skin cancer have been published." (PMID 38518996, 2024). "Chronic polycyclic aromatic hydrocarbon (PAH) exposure may activate the aryl hydrocarbon receptor (AhR) transcription factor affecting epidermal targets, thus contributing to skin cancer development." (PMID 39347184, 2024).
skin cancer (continued). "Interestingly, both environmental factors seem to interact on the level of enzyme activity and DNA damage and repair, thus illustrating the critical role of the AHR in either restraining or facilitating the development of skin cancer." (PMID 35311158, 2022). "To identify the different modes of action of the indirubin derivatives in the two skin cancer cells, we investigated in a first step whether the expression of the AhR differs." (PMID 35169210, 2022). "Hence, the development of therapeutic agents that regulate AhR activity is a promising strategy for the prevention and treatment of skin cancers." (PMID 35458697, 2022). "Please note that while we are focusing on the mentioned aspects other functions of the AHR system might fall short, which may be also relevant for the process of skin cancer development." (PMID 35311158, 2022). "Despite the fact that AhR plays an important role in various physiological processes in the skin, previous studies indicated the possible involvement of this receptor in skin cancer formation and progression." (PMID 34299117, 2021). "In support of this hypothesis, AHR has recently been found to be associated with UVR and air pollutant-induced carcinogenesis of skin cancer." (PMID 31552251, 2019). "In addition to the carcinogenic role of AHR activation, AHR also greatly contributes to the maintenance of various skin cancers." (PMID 31552251, 2019). "Taken together, these findings underscore the importance of AHR in the biology of skin cancers." (PMID 31552251, 2019). "Hence, it was postulated that cutaneous AHR signaling pathways contribute to the UVB-induced development of keratinocyte-derived skin cancers." (PMID 31795255, 2019). "The overexpression and activation of AHR are involved in the early development of skin cancers." (PMID 30144817, 2018). "AHR−/− mice developed approximately 50% less skin tumors than their AHR+/+ littermates." (PMID 30013037, 2018). "An animal study showed that AHR was essential for skin tumor induction by benzo[a]pyrene." (PMID 30144817, 2018). "Therefore, the canonical pathway activated by AhR may be responsible for premature skin aging, skin cancer, and the inhibition of apoptosis." (PMID 37445680, 2023). "Furthermore, AHR activation induced by UVB irradiation can activate the expression of cyclooxygenase-2, which is pro-inflammatory and associated with the development of skin cancer." (PMID 31552251, 2019). "Both overexpression and activation of AHR may participate in the early development of skin cancers." (PMID 30144817, 2018). "Thus, VRCZ/AhR/COX-2/PGE2 axis promotes the skin tumor progression." (PMID 29568008, 2018). "Moreover, the responses induced by AhR factor are dependent on whether the activation is acute or chronic in its nature, i.e., acute responses seem to be protective and adaptive, whereas in chronic inflammatory conditions, AhR signaling promotes premature aging and skin cancers." (PMID 35748903, 2022). "Indeed, blocking the AhR signaling activity could prevent or treat skin cancer." (PMID 35458697, 2022). "Topical application of known AhR antagonists, as some plant polyphenols (resveratrol, epigallocatechin-3-gallate), was found to have a protective role against UVB-induced skin cancer in mice." (PMID 35458697, 2022). "The critical role of AhR in PM- or BaP-induced cancerogenesis has been indicated by the lack of skin tumors in AhR(−/−) mice continuously exposed to airborne PM or BaP." (PMID 37445680, 2023). "Chronic topical application of organic extracts of airborne particulate matter (PM) results in skin cancer development in half of the AhR+/+ mice but in none of the AhR−/− ones." (PMID 35458697, 2022). "Although AHR expression levels do not differ significantly in various types of skin cancer, we observed a significant downregulation of AHRR expression in skin cutaneous melanoma (SKCN)." (PMID 33499346, 2021).
skin cancer (continued). "Although a few laboratory studies suggested that AHR played an important role in the pathogenesis of skin cancers, no clinical data have confirmed these results." (PMID 30144817, 2018). "There is no clear confirmation that AhR activation leads to the development of skin cancers." (PMID 33499346, 2021). "Although these laboratory studies indicated that AHR might play a role in the pathogenesis of skin cancers, to the best of our knowledge, no clinical data have confirmed these results." (PMID 30144817, 2018).